TBX1 (T-box transcription factor 1)
Diseases named in the same sentence as TBX1 in open-access papers (continued):
Sharing a sentence is not in itself a finding about the gene and the disease.
DiGeorge syndrome (continued). "TBX1 is a transcription factor involved in embryonic development and a key gene in 22q11.2 deletion syndrome (DiGeorge syndrome)." (PMID 33750431, 2021). "Tbx1 mutant mice are a widely used model of 22q11.2 deletion syndrome (22q11.2DS) because they manifest a broad spectrum of physical and behavioral abnormalities that is similar to that found in 22q11.2DS patients." (PMID 34552467, 2021). "During the 6-year study period, our institution cared for a total of 28 infants with DiGeorge syndrome (DGS) including 26 infants with 22q11.2 deletion and 2 infants with heterozygous pathogenic variants in TBX1 who had undergone newborn SCID screening." (PMID 34539671, 2021). "22q11 proximal deletion, also known as DiGeorge syndrome or velocardiofacial syndrome, involves more than 30 Mendelian genes; potential genes such as TBX1, COMT, UFD1L, GNB1L, TRXR2, MED15, and RANBP1 were researched to explore the phenotype/CNV correlation." (PMID 32863884, 2020). "The T-box transcription factor TBX1 has critical roles in the cardiopharyngeal lineage and the gene is haploinsufficient in DiGeorge syndrome, a typical developmental anomaly of the pharyngeal apparatus." (PMID 33015063, 2020). "DiGeorge syndrome deletion 22q11 was tested by TBX1 dosage using bioinformatic interpretation of NGS data." (PMID 32754152, 2020). "Reduced levels of Tbx1 in 22q11.2 deletion syndrome (22q11.2DS) impair the development of neural crest-derived mesenchymal cells that surround the 3rd PP, leading to thymic hypoplasia." (PMID 32922396, 2020). "TBX1 is a T-box transcription factor that maps to the center of the DiGeorge syndrome (DGS) chromosomal region on 22q11.2." (PMID 30691450, 2019). "A microdeletion in humans containing TBX1 and surrounding genes, including TXNRD2, has been linked to DiGeorge syndrome (22q11.2 deletion syndrome), the most common microdeletion disorder in humans." (PMID 31821332, 2019). "One important gene disrupted in 22q11.2 deletion syndrome is TBX1, which is inversely regulated by RA signaling." (PMID 31300413, 2019). "Mutations of TBX1 are known to cause DiGeorge syndrome (OMIM #188400) and velocardiofacial syndrome (OMIM #192430), and scoliosis is one of the clinical features, which is highly prevalent (47–49%) in association with these syndromes." (PMID 31417091, 2019). "Using mouse models, we found that two transcription factor genes, Tbx1, the gene for 22q11.2 deletion syndrome and Foxi3, genetically interact in the third pharyngeal pouch endoderm during thymus and parathyroid gland development." (PMID 31412026, 2019). "TBX1 haploinsufficiency is the major contributing factor in the development of congenital cardiovascular defects in the 22q11.2 deletion syndrome (22q11.2DS)." (PMID 30408103, 2018). "The TBX1 gene is haploinsufficient in 22q11.2 deletion syndrome (22q11.2DS), and genetic evidence from human patients and mouse models points to a major role of this gene in the pathogenesis of this syndrome." (PMID 30166330, 2018). "In humans, TBX1 is a major gene involved in 22q11.2 deletion syndrome (DiGeorge/velo-cardio-facial syndrome), a congenital disease characterized by cardiovascular defects and craniofacial malformations." (PMID 30451684, 2018). "Haploinsufficiency of the T-box transcription factor TBX1 is responsible for many features of 22q11.2 deletion syndrome." (PMID 30249045, 2018). "Tbx1 is also proposed as a major candidate for del22q11.2 deletion syndrome (or DiGeorge syndrome), characterized by serious craniofacial and cardiovascular defects, including TOF and common arterial trunk (CAT)." (PMID 29367466, 2018). "In this study, we showed that inactivation of Tbx1 in the AHF using Mef2c-AHF-Cre allele, results in a PTA that is also observed in the most seriously affected 22q11.2DS (velo-cardio-facial/DiGeorge syndrome) patients." (PMID 28346476, 2017).
DiGeorge syndrome (continued). "TBX1 has been shown to be a major determinant in 22q11 deletion syndromes (22q11DS), including Di George syndrome; hence, the influence of TBX gene activity in the developing foregut has recently attracted significant interest." (PMID 28503544, 2017). "This is also true in animal experiment where mice carrying extra copies of TBX1 gene display full clinical picture of 22q11.2 deletion syndrome." (PMID 27051557, 2016). "In zebrafish, Tbx1 is necessary for proliferation of the second heart field, and tbx1-null embryos mimic the heart defects seen in DiGeorge syndrome." (PMID 24973746, 2014). "This previously underappreciated morphogenetic role of mesodermal Tbx1 in pouch development helps to clarify the tissue-specific functions and molecular targets of this crucial DiGeorge syndrome gene during craniofacial development." (PMID 25142463, 2014). "TBX1 and CRKL haploinsufficiency is thought to cause the cardiac phenotype of the 22q11.2 deletion syndrome." (PMID 24998776, 2014). "In mouse models for the Cardio-Velo-Facial/Di George syndrome, defects in the development of second heart field derivatives, such as the outflow tract, arise from altered Tbx1 dosage, including overexpression." (PMID 24311985, 2013). "Although Tbx1 is the major candidate gene for DiGeorge syndrome, other genes are likely to function as modifiers." (PMID 24131868, 2013). "TBX1 is a molecular marker of the SHF and accruing evidence points to a causative role for this transcription factor in the pathogenesis of DiGeorge syndrome (DGS)." (PMID 23437302, 2013). "Based on a number of arguments (see Discussion), Vegfa has been proposed to interact genetically with Tbx1 and thereby function as a modifier of the DiGeorge syndrome." (PMID 22396765, 2012). "DiGeorge syndrome in humans is most commonly associated with mutation of the Tbx1 gene, and in mice, the terminal DGS phenotypes of Tie2Cre/Nrp1 and Tbx1 mutants are similar." (PMID 22396765, 2012). "Our results demonstrate that impairment of VEGF-dependent endothelial pathways leads to a spectrum of DiGeorge syndrome-type malformations, through processes that are distinguishable from those controlled by Tbx1." (PMID 22396765, 2012). "Only eight of the events (all hotspot sites) associated with genomic disorders, including 22q11.2 deletion (TBX1, DiGeorge syndrome), 17p12 duplication (PMP22, Charcot-Marie-Tooth disease), and 15q11.2q13.1 duplication (UBE3A and SNRPN)." (PMID 22102821, 2011). "Models developed for for del22q11.2 (DiGeorge syndrome) enabled to identify TBX1 as a candidate gene for the pathology." (PMID 21358991, 2010). "Tbx1, the gene responsible for velo-cardio-facial syndrome/DiGeorge syndrome in humans, is required for ear development in mice." (PMID 19476657, 2009). "Loss of Tbx1 in mice results in a shortened distal OFT with development of the anterior ICVS impacted, and we have identified comparable phenotypes in the zebrafish tbx1 mutant, mirroring the congenital heart malformations seen in 22q11.2 deletion syndrome (DiGeorge)." (PMID 39460530, 2025). "TBX1 plays a critical role in the normal formation of pharyngeal arch and pouch-derived structures during embryogenesis, and its deletion contributes significantly to the characteristic features of DiGeorge syndrome." (PMID 40084332, 2025). "In addition, as presented in the introduction, Tbx1 is the primary genetic driver of CF phenotypes in DiGeorge Syndrome." (PMID 40982554, 2025). "Hence, the objective of this study is to utilize in-silico analysis to investigate the role of the TBX1 gene within the context of 22q11.2 deletion syndrome." (PMID 38905172, 2024). "Notably, we also identified significant variants in the causative genes of rare neurodevelopmental disorders sharing comorbidities with FASD, including STRA6 (Matthew–Wood), SOX9 (Campomelic Dysplasia), FDG1 (Aarskog), and 22q11.2 deletion syndrome (TBX1)." (PMID 38785976, 2024).
DiGeorge syndrome (continued). "However, we also found variants in genes associated with primary hyperparathyroidism (GCM2), renal hypophosphatemia with or without rickets (SLC34A1, SLC34A3, SLC9A3R1, VDR, and CYP27B1), DiGeorge syndrome (TBX1 and NEBL), and hypophosphatasia (ALPL)." (PMID 38586466, 2024). "Genomic deletions at chromosomal region 22q11, which includes the TBX1 locus, have been reported in patients with DiGeorge syndrome, supporting its role in the development of the pharyngeal region and the heart and highlighting copy number alterations in deregulation." (PMID 38203204, 2023). "However, in support of our preliminary biological conclusions, a prior murine model of Tbx1 haploinsufficiency, a “critical gene” within the 22q11.2 deletion syndrome locus, also exhibited a similar phenotype of premature neuronal differentiation." (PMID 37169815, 2023). "In addition, TBX1 (OMIM #602054), which is located in the center of the region associated with DiGeorge syndrome (OMIM #188400), is partially deleted (six deleted exons out of a total of nine exons) in patient n." (PMID 37186221, 2023). "Here, the authors use single cell analyses to show how these cells are altered non-autonomously by loss of Tbx1, the major gene for 22q11.2 deletion syndrome." (PMID 36941249, 2023). "Kobrynski and Sullivan report that the specific gene responsible for the clinical presentation of velocardiofacial syndrome, called the TBX1 gene, was identified in 2001; however, at the locus of chromosome 22 in which the deletion occurs, there are more than 35 other genes." (PMID 36010058, 2022). "At our Department, the typical DiGeorge syndrome (proximal A-D 22q11.11 deletion, including TBX1 gene), Williams syndrome and the deletion form of Prader-Willi syndrome are diagnosed by fluorescent in situ hybridization (FISH), therefore these cases are not included in this study." (PMID 36320065, 2022). "TBX1 is responsible for most of the physical malformations present in 22q11.2 deletion syndrome, or DiGeorge syndrome, which is a congenital disease that has been implicated in various behavioral abnormalities including schizophrenia and other neuropsychiatric/behavioral disorders." (PMID 35370858, 2022). "Finally, TBX1 encodes a key protein necessary for the normal development of large arteries (cases of 22q11.2 deletion syndrome contain TBX1)." (PMID 34208491, 2021). "Additionally, interactions between Tbx1 and RA signaling have been demonstrated in a mouse model of DiGeorge syndrome." (PMID 34307338, 2021). "Moreover, some studies have reported that knockout and overexpression of Tbx1 in mouse results in the phenotypes of 22q11.2 deletion syndrome." (PMID 34977180, 2021). "We investigated whether Tbx1, the gene for 22q11.2 deletion syndrome (22q11.2DS) and Foxi3, both required for segmentation of the pharyngeal apparatus (PA) to individual arches, genetically interact." (PMID 31412026, 2019). "Together, we show that Tbx1 and Foxi3 are important for regulating PA segmentation through cellular and genetic mechanisms that may be critical in 22q11.2 deletion syndrome patients." (PMID 31412026, 2019). "In human, TBX1 has been identified as a major candidate gene for 22q11.2 deletion syndrome." (PMID 30451684, 2018). "Tbx1 null mice replicate the cardiovascular features seen in patients with DiGeorge syndrome." (PMID 29956664, 2018). "Recently, work in chick suggested that signalling via CXCR4 in neural crest cells (NCCs) has a role in the 22q11.2 deletion syndrome (22q11.2DS), a disorder where haploinsufficiency of the transcription factor TBX1 is responsible for the major structural defects." (PMID 30408103, 2018). "Therefore, our analysis of Tbx1-null mutants provides a better understanding of the etiology of the 22q11.2 deletion syndrome and has direct implications in establishing clinical diagnosis in cases where patients present failure in neck-associated functions." (PMID 30451684, 2018).
DiGeorge syndrome (continued). "Especially, T-box factors such as Tbx1, Tbx2, Tbx3, Tbx5, Tbx18 and Tbx20 are described to be involved in virtually all steps of cardiogenesis and mutations are associated with developmental syndromes and cardiac abnormalities like DiGeorge syndrome (Tbx1) or Holt-Oram syndrome (Tbx5)." (PMID 27907103, 2016). "In addition, Tbx1, another T-box gene that has been described to affect proliferation of IPCs is correlated with DiGeorge Syndrome leading to a decrease in supragranular layer neurons." (PMID 24927931, 2015). "Gene dosage evaluation in a mouse model of 22q11 deletion/DiGeorge syndrome has shown that disruption of genes other than Tbx1 may be potential contributors for developmental disorders including autism associated with this syndrome." (PMID 23840741, 2013). "In summation, Tie2Cre/Nrp1 mutants have a high or complete penetrance of cardiac outflow tract, great vessel, pharyngeal organ, and craniofacial defects that collectively typify DiGeorge syndrome in humans and that are also seen with high or complete penetrance in Tbx1 and Vegfa mutant mice." (PMID 22396765, 2012). "Tbx1 is the first dosage-sensitive gene identified in models for the DiGeorge syndrome (DGS)/velocardiofacial syndrome (VCFS), a congenital disorder characterized by neural-crest-related developmental defects." (PMID 40982554, 2025). "Notably, patients with point mutations in TBX1 display characteristic phenotypes of 22q11.2 deletion patients, although they do not develop the full spectrum of DiGeorge syndrome." (PMID 37125615, 2023). "However, our patient with a TBX1 variant (P3) did not have any physical features of velocardiofacial syndrome, only diminished lymphopoiesis." (PMID 34539671, 2021). "TBX1 (T-box transcription factor 1) is a major candidate gene that likely contributes to the etiology of velo-cardio-facial syndrome/DiGeorge syndrome (VCFS/DGS)." (PMID 34332615, 2021). "In particular, cell shape changes in the SHF of mouse embryos lacking the 22q11.2 deletion syndrome candidate gene Tbx1 are associated with loss of basal filopodia and elevated aPKCz levels contributing to decreased proliferation and ectopic differentiation in the Tbx1−/− DPW12." (PMID 28357999, 2017). "In addition, 5 of 20 patients who were clinically suspected of 22q11.2 deletion syndrome but with neither a 22q11.2 deletion nor a TBX1 gene mutation had a CHD7 mutation." (PMID 27957375, 2016). "The TBX1 gene, a member of a phylogenetically conserved T-box gene family of DNA-binding transcription factors, is mapped to the 22q11.2, and is hypothesised to be responsible for the cardiac phenotype of 22q11.2 deletion syndrome." (PMID 24998776, 2014). "The TBX1 gene encodes a T-box transcription factor that maps to the 22q11.2 region, which is hemizygously deleted in individuals with velo-cardio-facial syndrome and DiGeorge syndrome (VCFS/DGS; MIM #: 192430/188400)." (PMID 24797903, 2014). "Furthermore, the homozygous loss of Tbx1, related to the DiGeorge syndrome phenotype, leads to thymic a/hypoplasia in humans, while mice heterozygous for a null allele of Tbx1 show a mild phenotype without thymus anomalies." (PMID 23874334, 2013). "Genome‐wide, methylation changes in DBAS overlapped significantly with those of Mowat‐Wilson syndrome (ZEB2) and Velocardiofacial syndrome (VCFS; TBX1, DGCR8), suggesting shared downstream developmental pathways affected by ribosomal stress." (PMID 41247002, 2026). "T-box transcription factor 1 (TBX1) is a pivotal gene involved in embryonic development, particularly significant in DiGeorge syndrome." (PMID 40084332, 2025). "The phenotypic similarity between CHARGE syndrome and 22q11.2 deletion syndrome is also apparent in mice with haploinsufficiency of CHD7 and TBX1." (PMID 27957375, 2016).
DiGeorge syndrome (continued). "Genes that may influence the phenotype may be similar to genes involved in the same deleted region in DiGeorge syndrome (DGS; OMIM 188400) and velocardiofacial syndrome (VCFS; OMIM 192430) (mainly TBX1, HIRA, CRKL)." (PMID 36226175, 2022). "Several neural crest regulatory molecules are known to cause ear/kidney syndromes with variable expression of both ear and kidney phenotypes (e.g., EYA1, SIX1, SIX5, CHD7, MASP1, TBX1), involved in BOR/BO syndrome, CHARGE syndrome, 3MC syndrome and DiGeorge syndrome." (PMID 32585897, 2020). "Among them, CRKL, TBX1, TXNRD2, GP1BB were known to be involved in DiGeorge syndrome." (PMID 26742958, 2016). "The absence of TBX1, in 22q11.2 deletion syndrome (DiGeorge syndrome) is responsible for the majority of characteristic features of this disease (the absence of node is illustrated in red)." (PMID 27876057, 2016). "Homozygous Tbx1 mutant mice and tbx1 mutant zebrafish (van gogh, vgo) recapitulate the major structural defects observed in patients with severe DiGeorge syndrome, including heart, thymus and craniofacial defects, but do not recapitulate all aspects of human DiGeorge syndrome." (PMID 37125615, 2023).